MMP9 (matrix metallopeptidase 9)
Diseases named in the same sentence as MMP9 in open-access papers (continued):
Sharing a sentence is not in itself a finding about the gene and the disease.
Stroke (continued). "The fifth group included two studies that reported outcomes related to the utility of MMP-9 in the risk stratification of stroke survivors." (PMID 36278689, 2022). "In a later study using photothrombotic stroke in mice, it was postulated that the rapid activation of MMP-9 secreted from pericyte somata degraded underlying TJ complexes resulting in plasma leakage between the pericyte somata and the bordering capillary wall." (PMID 36139398, 2022). "The gut microbiota modulates the inflammatory response and MMP9 that are associated with hemorrhagic transformation after stroke." (PMID 34591349, 2022). "The MMP-9 inhibitor minocycline reduced the risk of HT after tPA in animal models, and the Minocycline to Improve Neurologic Outcome in Stroke (MINOS) human trials showed a decrease in plasma MMP-9 levels in patients treated with intravenous tPA." (PMID 34917010, 2021). "For example, VEGF and MMP‐9 cause blood‐brain barrier (BBB) damage in the acute phase of stroke and exacerbate neurovascular dysfunction, but they also promote compensatory angiogenesis in the chronic phase." (PMID 33314664, 2021). "For example, MMP‐9 is known to be released after stroke, causing NVU dysfunction by disassembling the extracellular matrix." (PMID 33314664, 2021). "Transmigrated leukocytes are the primary source of MMP-9, causing BBB interruption following stroke through increasing transcriptional activity and activation of pre-MMP-9 by N-nitrosylation and oxidation." (PMID 34576209, 2021). "Recent work from our group has established a causal link between increased activity of both ABCB1 and MMP-9 on the one hand and the NF-κB pathway on the other hand under stroke conditions." (PMID 34483846, 2021). "Many studies have shown that the level of matrix metalloproteinase (especially MMP9) increases after stroke, and is associated with BBB disruption." (PMID 34992531, 2021). "Further, previous studies have reported that MMP-9 activity is positively correlated with BBB breakdown after stroke and linked to tPA-induced hemorrhage in stroke patients and animal models." (PMID 34299322, 2021). "Expression of MMP-9 levels is high in brain tissue after stroke, and during the acute stage, high circulating MMP-9 levels are related to an increased risk of mortality, indicating a contribution of MMP-9 to ischemic brain injury." (PMID 34898370, 2021). "Expectations have been high for MMP-9 (matrix metalloproteinase-9) as a stroke diagnostic biomarker because of its role in response to brain injury via its involvement in extracellular matrix degradation." (PMID 33633673, 2021). "Inhibitors of PARP-1, namely JPI-289, FR247304, and MP-124, significantly maintained the TJs and reduced the MMP9 levels, brain swelling, HT occurrence, infarction size, and functional deficiency in stroke." (PMID 34248961, 2021). "Nevertheless, the present study revealed that QSYQ prevented the increase in MMP-9 in the cortex of stroke mice after tPA treatment, suggesting that inhibition of MMP-9 expression underlies the protective effect of QSYQ on basement membrane integrity." (PMID 35095486, 2021). "High MMP-9 values in the early phase of stroke have been associated with poor disability outcomes and increased mortality risk." (PMID 34445740, 2021). "Our analysis found that ischaemic patients with both higher serum TIMP‐1 (≥184.2 ng/mL) and MMP‐9 (≥462.6 ng/mL) levels had higher risk of post‐stroke cognitive impairment." (PMID 32431079, 2020). "For instance, the expression and activity of matrix metalloproteinase-9 (MMP9) were significantly increased during stroke in human and were associated with the early phase of DVT resolution." (PMID 33092540, 2020). "We systematically reviewed the literature to investigate the association of circulating MMP-9 and c-Fn levels and MMP-9 rs3918242 polymorphism with the risk of three outcome measures after stroke." (PMID 33329294, 2020).
Stroke (continued). "In summary, our results provide a basis for deeper mechanistic studies on pericytes as inducers of BBB disruption in stroke, and potentially other cerebrovascular diseases were MMP-9 has been implicated in microvascular pathology." (PMID 33505320, 2020). "After stroke, MMP-9 deficient mice were associated with less damage and a better preservation of BBB integrity, and MPP-9 inhibition was translated into neuroprotection after stroke." (PMID 32357544, 2020). "A miR491-5p decrease leads to increased risk of cerebral ischemia and worsening stroke-induced BBB disruption by directly regulating expression of MMP9." (PMID 31543756, 2019). "MMP‐9 polymorphisms were independently associated with severe stroke and higher risk of END, and prestroke antithrombotic treatment was associated with less severe stroke and lower risk of END in patients with AF." (PMID 31012282, 2019). "A previous study that followed patients for 10 years found that high MMP9 levels were associated with a higher incidence of stroke and cardiovascular death." (PMID 31583048, 2019). "Stroke is regarded as the one of the leading causes of death in the world and MMP-9 levels in the blood have been suggested to represent a suitable biomarker supporting its prognosis." (PMID 30935029, 2019). "With this multi‐center, prospective, observational study, we investigated the possible role of MMP‐9 gene polymorphisms in initial stroke severity and END risk in IS patients with AF." (PMID 31012282, 2019). "MMP-9, upregulated 15–48 h after the onset of ischaemia, has also been intimately linked to stroke pathology, with higher serum levels, a predictor of poor disease outcome." (PMID 31281252, 2019). "Both in-vivo after ischemic stroke and in-vitro using OGD model of stroke with primary rat cortical neurons, it has been reported that MMP9 is activated and expressed in neuronal nuclei and associated with delayed neuronal death." (PMID 29896433, 2018). "Both mrProANP and A-FaBP have been proposed as diagnostic and prognostic biomarkers in adults with stroke We found higher A-FaBP levels in the septic subjects with neurologic dysfunction, but only MMP-9/TIMP-1 ratio was associated with 6-month outcome." (PMID 27089280, 2016). "Not only have neutrophils been implicated as a source of MMP-9 following stroke which contributes to injury and barrier dysfunction, they have also been suggested to be the source of MMP-9 following tPA treatment." (PMID 26973468, 2016). "The aim of this study was to evaluate the association between the C(-1562)T MMP-9 gene polymorphism and risk of stroke." (PMID 26330106, 2015). "There are only few studies that evaluated association of MMP-9 gene polymorphism with susceptibility to stroke or functional outcome after stroke." (PMID 26330106, 2015). "The aim of this study was to evaluate the association between the C(-1562)T functional polymorphism in the MMP-9 gene and risk of stroke." (PMID 26330106, 2015). "In the ischemic injury models, MMP9 activity was detected in endothelial cells, astrocytes, and neurons, and HMGB1 released during stroke was implicated in activation of MMP9 via TLR4 signaling." (PMID 25879213, 2015). "The TT genotype and T allele frequencies of MMP-9 C/T polymorphism were significantly increased in stroke patients." (PMID 26330106, 2015). "Circulating levels of MMP9 have been proved associated with poor outcomes in stroke patients treated with tissue plasminogen activator (rtPA)." (PMID 26074872, 2015). "The -1562 C/T (rs3918242) polymorphism in the MMP-9 gene was genotyped in 322 patients with stroke (90 % had ischemic stroke) and 410 healthy control subjects." (PMID 26330106, 2015). "MMP-9 induction is linked with tissue plasminogen activator (tPA)-induced hemorrhage in stroke patients and animal models." (PMID 25418536, 2014).
Stroke (continued). "Genetic deletion of CaMKK β or CaMK IV increased hemorrhagic transformation after stroke, and this was associated with both increased MMP9 activity and loss of the blood brain barrier (BBB) protein collagen IV." (PMID 25331941, 2014). "Loss of CaMKK β resulted in significantly upregulated MMP-9 levels 6 hours after stroke (n = 3 per stroke group, p < 0.05)." (PMID 25331941, 2014). "Third, both CaMKK β and CaMK IV KO mice exhibited increased hemorrhagic transformation after stroke, and this was associated with both increased MMP9 activity and the loss of the BBB protein collagen IV." (PMID 25331941, 2014). "The overexpression of MMP-9 increases the risk of rupture of the fibrous cap of the atherosclerotic plaque, and thus represents a key mechanism in thrombotic events such as strokes or acute coronary syndromes." (PMID 24324801, 2013). "Clinical data have also shown that plasma and brain levels of MMP-9 are elevated in patients with acute ischemic stroke, and delayed tPA therapy causes a further increase in plasma MMP-9 in stroke patients." (PMID 23565108, 2013). "Defining the precise role of plasma MMP-9 after ischemic stroke will have important diagnostic implications for stroke and help in the development of therapeutic strategies aimed at modulating plasma MMP-9." (PMID 23565108, 2013). "Severe neurological deficits and brain tissue loss positively correlate with elevated MMP-9 levels in stroke patients, who are at higher risk for developing life-threatening cerebral edema and hemorrhage." (PMID 23522154, 2013). "Acting through protease-activated receptor-1, thrombin activates MMP-9 in astrocytes, a mechanism linked to the pathogenesis of intracerebral hemorrhage after administration of tissue plasminogen for treatment of stroke." (PMID 22507553, 2012). "Marker of tissue injury MMP-9 and pro-inflammatory cytokine IL-6 were associated with acute lesion volume and with admission National Institutes of Health Stroke Scale (NIHSS)." (PMID 21871109, 2011). "The MMP9 R279Q polymorphism has been associated with increased intima-media thickness, an independent predictor of MI and stroke risk." (PMID 21887284, 2011). "Specifically, we found that patients having the MMP9 R668Q AA genotype who were treated with chlorthalidone have a decreased risk of combined CHD but an increased risk of stroke compared to patients treated with amlodipine." (PMID 21887284, 2011). "The second major proteolytic enzyme in the brain, MMP9 (also known as gelatinase B), has been heavily implicated in many types of CNS injury including stroke, ischemia and trauma." (PMID 21906275, 2011). "Our data suggest associations between the MMP9 R279Q polymorphism and stroke and between the MMP12 N122S polymorphism and combined CHD." (PMID 21887284, 2011). "In the present study, the role of MMP-2 and MMP-9 genetic variants in stroke recovery was investigated in 546 stroke patients." (PMID 20222942, 2010). "In the present study we tested the impact of genetic variants in MMP-2 and MMP-9 in stroke recovery, in a population sample of 546 patients evaluated for stroke outcome at three months after the stroke event." (PMID 20222942, 2010). "The formation of oedema and opening of the blood-brain barrier in stroke is associated with enhanced expression of metalloproteinase-9 (MMP-9) and tissue inhibitor of metalloproteinase-1 (TIMP-1)." (PMID 19497125, 2009). "Elevated MMP-9 levels in cerebrospinal fluid and plasma are consistently associated with hemorrhagic transformation following thrombolytic therapy in stroke, highlighting its dual significance as both a mechanistic driver of vascular injury and a clinically relevant biomarker." (PMID 41304763, 2025).
Stroke (continued). "The rapid activation of MMP‐9 secreted from pericellular cell bodies was thought to have caused the underlying TJ complex to be degraded in a later study of photothrombotic stroke in mice, which resulted in plasma leakage between pericellular cell bodies and nearby capillary walls." (PMID 41395456, 2025). "Knowing that, patients with higher MMP-9 levels might benefit from more intensive follow-up protocols to mitigate the risk of adverse outcomes such as stroke or cognitive decline." (PMID 40364266, 2025). "Interestingly, MMP-9 has also been associated with blood-brain barrier dysfunctions related to seizures, stroke, and in animal models of brain injury and aging." (PMID 38431757, 2024). "Moreover, elevated MMP-9 levels have been associated with hemorrhagic conversion after r-tPA or mechanical thrombectomy treatment in stroke patients." (PMID 38592044, 2024). "Our findings have been corroborated in numerous studies, i.e., that elevated levels of MMP-9, particularly in the acute phase of stroke, are associated with worse outcomes, and a sustained decrease in MMP-9 levels following several days of treatment is indicative of a favorable prognosis." (PMID 38891934, 2024). "In addition, increased blood MMP9 activity has been previously associated with worse stroke outcome." (PMID 39112714, 2024). "The most intensively investigated were SNPs at MMP-9 gene, which influenceMMP-9 activity and, respectively, cardiovascular mortality in patients with coronary heart disease, sex-related carotid atherosclerosis stiffness and elevated risk of stroke." (PMID 36835040, 2023). "Furthermore, patients with the genotype variants (CT + TT) of the MMP-9 polymorphism had larger stroke lesion volumes than carriers of the CC genotype (p = 0.036)." (PMID 37206663, 2023). "Additionally, positive effects of mesenchymal stem cell treatment in experimental stroke and recanalization have been linked with reduced risk of HT due to reduced MMP-9 activation." (PMID 36835040, 2023). "The risk for the development of ischemic stroke in the Indian population was 10.71-times higher when the allele T occurs vs. allele C. This group of researchers also revealed that methylation in the MMP-9 gene promoter decreased the risk of stroke (aOR = 0.23; P < 0.001)." (PMID 37206663, 2023). "Most studies, as well as meta-analyses, indicate the association of the presence of the T allele of the MMP-9-1562C/T polymorphism in patients with a higher risk of stroke, as well as with early neurological deterioration and higher mortality compared to allele C carriers." (PMID 37206663, 2023). "Furthermore, in patients with AF,MMP-9 gene polymorphism appears to be associated with the severity of stroke and the risk of early neurological deterioration (END)." (PMID 36835040, 2023). "The association of an MMP9 SNP or MMP SNP‐SNP interaction with other subtypes of stroke or transient ischemic attacks is unknown." (PMID 34984852, 2022). "Besides, insulin-like growth factor 1 (IGF1) and aquaporin-4 (AQP4) decreased, while matrix metalloproteinase-9 (MMP9) heightened after stroke in brain ABCA1 deficiency mice." (PMID 35935038, 2022). "The changes of gut microbiota, peripheral inflammation, and SCFAs may further regulate MMP9 level and affect blood‐brain barrier permeability, contributing to an increase in HT susceptibility after stroke." (PMID 34591349, 2022). "Interestingly, the associations observed between elevated levels of MMP-9 and higher risks of death and major disability among stroke patients were characterized by a dose–response pattern." (PMID 36278689, 2022). "We enrolled a relatively large sample and found that the expression of the MMP-9-related miRNA miR-491-5p could reduce the risk of poor functional outcome after stroke." (PMID 36009063, 2022).
Stroke (continued). "Nevertheless, human blood is a complex sample matrix that can be difficult to access the relevant stroke biomarkers, such as cellular fibronectin (c-Fn) and matrix metallopeptidase 9 (MMP9) —strongly associated with ischemic stroke screening in clinical studies for more than five decades." (PMID 36296077, 2022). "However, the underlying mechanism of the deleterious effect of MMP-9 during stroke still lacks adequate evidence." (PMID 36009063, 2022). "Elevated MMP-9 levels following stroke are associated with the disruption of BBB and brain edema." (PMID 34393790, 2021). "MMP-9 inhibition, while potentially beneficial to reduce the risk of HT, may also impair post-stroke vascular remodeling and impair recovery." (PMID 34054705, 2021). "However, these events caused by MMP‐9 during the acute phase of stroke appear to be necessary for compensative angiogenesis and neurogenesis during the chronic phase." (PMID 33314664, 2021). "Interestingly, a concomitant influenza A virus infection and stroke led to elevated systemic MMP-9 levels that were associated with increased BBB disruption and intracerebral bleeding after thrombolysis." (PMID 34572077, 2021). "MMP-9 methylation decreased the risk of stroke (aOR = 0.23; P < 0.001)." (PMID 35002488, 2021). "In parallel, independently of the presence of vascular risk factors, elevated serum MMP-9 levels are associated with mild (25.6% of patients) and severe (27.4%) cognitive impairment 3 months following stroke according to the Mini-Mental State Examination and Montreal Cognitive Assessment." (PMID 34566627, 2021). "In this context, new miniaturized biosensing POC prototypes are under development for fast multiplex monitoring of different biochemical and genetic pathways potentially associated with stroke (e.g., MMP9, TNF-α, IL6, S100B, GFAP, microRNA) in minimally invasive blood samples." (PMID 34440560, 2021). "MMP-9 induction is associated with tPA-induced hemorrhage in stroke patients and animal models." (PMID 34299322, 2021). "We hypothesized that inhibition of CD147 would decrease levels of MMP-9, reduce histological damage, and enhance long-term functional and cognitive outcomes in aged animals, which have a greater risk of post-stroke hemorrhagic transformation." (PMID 32191628, 2020). "Permanent stroke causes more profound inflammatory responses and higher levels of MMP-9 in blood." (PMID 32843630, 2020). "The most interesting finding in this study was that the variants of rs3918242 and rs3787268 in MMP‐9 gene were independent predictors for initial stroke severity, and rs1056628 AC/CC and rs3918242 CT/TT were independently associated with higher risk of END after adjusting for covariates." (PMID 31012282, 2019). "In this study, we found that the variants of rs3918242 and rs3787268 in MMP‐9 gene were independent predictors for initial stroke severity, and rs1056628 AC/CC and rs3918242 CT/TT were independently associated with the higher risk of END after adjusting for covariates in IS patients with AF." (PMID 31012282, 2019). "Finally, the main aim of this study was to investigate the association of MMP‐9 gene polymorphisms with initial stroke severity and the risk of END in IS patients with AF." (PMID 31012282, 2019). "Moreover, brain-derived MMP-2 and MMP-9 activated by ischemia are associate with hemorrhagic transformation, partly explaining the high incidence of hemorrhage of stroke KO mice." (PMID 30622459, 2018). "Furthermore, rt-PA was shown to upregulate MMP-9 levels in vivo in a rat model of stroke, emphasizing the impact of MMP-9 activation in rt-PA-associated side effects, such as HT." (PMID 30131754, 2018). "Notably, in this study, S1RA reduced oedema and decreased the MMP-9 activation associated with stroke." (PMID 28779350, 2018).